EDDM13 (epididymal protein 13)
Gene: Protein-coding gene on chromosome 19 (56,272,748 to 56,310,454, forward strand). Ensembl gene ENSG00000267710.
Subcellular location: Secreted
Gene Ontology:
Cellular component: extracellular region
Genetic constraint (gnomAD): Loss-of-function variants: 8 observed, 4.95 expected, observed/expected ratio (o/e) 1.62, 90% interval 0.87 to 1.94. That is too few expected variants to judge how well the gene tolerates losing a copy. Missense variants: 49 observed, 43.21 expected, observed/expected ratio (o/e) 1.13, 90% interval 0.9 to 1.44. Synonymous variants: 20 observed, 18.9 expected, observed/expected ratio (o/e) 1.06, 90% interval 0.74 to 1.53.
Homologues: Orthologues: chimpanzee EDDM13 (99% identical), macaque EDDM13 (95% identical), rabbit EDDM13 (78% identical), mouse Eddm13 (71% identical), dog EDDM13 (70% identical), pig EDDM13 (68% identical), rat Eddm13 (47% identical).